IL6 (interleukin 6)
Diseases named in the same sentence as IL6 in open-access papers (continued):
Sharing a sentence is not in itself a finding about the gene and the disease.
COVID-19 (continued). "Heatmap constructs further illustrated that the major increase in serum soluble mediators observed in pregnant women with convalescent COVID-19 occurred in pro-inflammatory cytokines, namely IL-6, TNF-α, IL-12, IFN-γ and IL-17." (PMID 37122732, 2023). "Multiple regression analysis showed that BMI (p = 0.045), IL-6 (p = 0.03), and MAFLD (p < 0.05) are significant independent risk factors for a poor COVID-19 outcome." (PMID 37629728, 2023). "Such an informative revelation suggests IL-6 as a basic determinant to predict long COVID-19 or at least inform on the “early stage” of long COVID-19." (PMID 37095536, 2023). "On the contrary, proinflammatory cytokine IL-6 is believed to be a marker of poor prognosis in COVID-19, as has also been observed in a recent study." (PMID 37686388, 2023). "Of note, at 10 μM, MB-905 also diminished SARS-CoV-2-induced TNF and IL-6 levels, a desired feature for antivirals against COVID-19." (PMID 36639383, 2023). "The current study is aimed at evaluating the role of IL-1 or IL-6 antagonists in controlling the worsening of mild and moderate COVID-19 cases and preventing them from becoming severe." (PMID 37046952, 2023). "Recent researchers also found that although the level of IL-6 in chronic COVID-19 patients was much higher than that in mild and moderate cases, the levels of CD4+ T cells, CD8+ T cells, and NK cells were lower, indicating immunosuppression." (PMID 37124230, 2023). "In elderly obese patients with COVID-19, elevated C-reactive protein (CRP), ferritin, and interleukin 6 (IL-6) levels were strongly associated with critical disease." (PMID 37628963, 2023). "Multiple cases of acute pancreatitis in patients with COVID-19 have been reported in the literature and altered serum cytokine levels of increased IL-6, IL-8, and IL-10 were found to be similar in cases of severe acute pancreatitis and in cases of COVID-19." (PMID 36672197, 2023). "Serum concentrations of proinflammatory cytokines and chemokines—including IFN-γ, TNF-α, IP-10, G-CSF, IL-2, IL-6, IL-8, IL-9, IL-10, and IL-17—were increased in patients with severe COVID-19 and strongly correlated with disease outcome." (PMID 36776881, 2023). "Interleukin-6 (IL-6) is an important COVID-19 biomarker in human body fluids that can be used as a reference to monitor COVID-19 in real-time and therefore to reduce the risk of virus transmission." (PMID 37234896, 2023). "Patients with serious COVID-19 illness had high IL-6, IL-8, and TNF-α levels, along with higher neutrophil and monocyte counts." (PMID 37754237, 2023). "We and others showed that plasma levels of IL-6 significantly positively correlated with progression of sepsis and COVID-19." (PMID 36776891, 2023). "Markers of hyperinflammation, degree of lymphopaenia, neutrophil levels, TNF-α, INR levels, and proinflammatory cytokines (interleukin (IL)-6 and IL-8) were significantly increased in COVID-19 patients compared to healthy controls (p < 0.05, 95% CI)." (PMID 37731491, 2023). "First, the admitted COVID-19 patients in this study were treated differently as corticosteroids, and interleukin-6 antagonists are now standard of care for hospitalized patients with hypoxemia." (PMID 37622126, 2023). "The pooled estimate of IL-6 revealed a mean value of 20.92 pg/ml (95% CI = 9.30–32.54 pg/ml, I2 = 100%, P < 0.01) for long COVID-19 patients." (PMID 37095536, 2023). "Follow-up of the 16 COVID-19 patients showed that with an increase in hsTnI, IL6 expression increased significantly (P<0.05)." (PMID 37564653, 2023). "This led to the beginning of several randomized clinical trials conducted to assess the efficacy of IL-6 antagonists in patients with COVID-19." (PMID 37384095, 2023). "Compared with the asymptomatic group, patients with COVID-19-related symptoms were younger, and exhibited higher IL-6 and lower post-infection phosphate levels (p < .05)." (PMID 37501590, 2023).
COVID-19 (continued). "We did not identify a direct positive relationship between the levels of leptin and IL-6 in hospitalized COVID-19 patients." (PMID 36509969, 2023). "The early usage of tocilizumab to block IL-6/IL-6R pathway activity and cytokine storm has been applied in patients with severe COVID-19 and received positive outcome." (PMID 36960050, 2023). "They reported that DNA damage was positively correlated with interleukin 6 (IL-6) concentration and negatively correlated with platelet count in COVID-19 patients." (PMID 37112613, 2023). "Among COVID-19 patients, the highest reported serum concentration of IL-1 β level was 140 pg/mL, whilst IL-6’s was 249.0 pg/mL, and TNF-α’s was 151.59 pg/mL." (PMID 37106750, 2023). "Monocyte-derived macrophages, which are the first responders to viral infections among the immunoregulatory cells, mainly secrete IL-6 and are the main generators of the inflammatory response in COVID-19 patients." (PMID 36982991, 2023). "Despite the fact that IL-6 is considered a particularly important cytokine in chronic inflammatory diseases and in the pathogenesis of COVID-19, it is still a predictor of its progression." (PMID 37484856, 2023). "Post-COVID-19 serum stimulated the synthesis of IL-6 in CAEC (+43%, p < 0.001) as compared to cells treated with the control serum." (PMID 38188630, 2023). "In severe cases of COVID-19, multiple studies have indicated higher levels of IL-2, IL-6, IL-7, IL-10, CXCL10(IP-10), CCL2 (MCP-1), TNF-α, CCL3(MIP-1α), and G-CSF when compared to patients with mild and moderate infections." (PMID 37834246, 2023). "Patient-related factors include immunosuppression from routine use of dexamethasone and interleukin-6 inhibitors for COVID-19." (PMID 36451285, 2023). "Interleukin-6 (IL-6) levels significantly increase in patients with COVID-19, while IL-8 remains relatively low." (PMID 38585537, 2023). "Therapies targeting IL-6, such as tocilizumab, have been investigated in the management of severe COVID-19 cases with systemic inflammation." (PMID 38248752, 2023). "In particular, the serum level of IL-6 is positively correlated with the severity of COVID-19 and is considered to be an indicator of disease severity." (PMID 38351911, 2023). "IL-6 plays crucial roles in multiple pathological processes including cytokine storm that mediates pathological processes such as COVID-19-induced syndromes and fever." (PMID 37325623, 2023). "In these studies, the production and sialylation of A1AT are increased in COVID-19, but this anti-inflammatory response is overwhelmed in severe illness, with the IL-6: A1AT ratio being markedly higher in patients requiring ICU admission." (PMID 36831051, 2023). "A correlation with worse clinical outcome in COVID-19 and high levels of IL-6 and TNF alpha has previously been reported." (PMID 37614753, 2023). "These trends are similar to other studies that demonstrated that HIV infection is associated with ICU admission, mechanical ventilation, intubation, interleukin-6, and clinical severity of COVID-19 inpatient services." (PMID 36909058, 2023). "The plasma levels of IL-6 and IL-10 (P<0.0001, respectively) were significantly increased in patients with COVID-19 as compared to the HC." (PMID 37207201, 2023). "Emerging evidence indicates that blocking IL-6 signaling during acute COVID-19 can mitigate enduring epigenetic changes in monocytes." (PMID 38090572, 2023). "According to the f test of the One-Way ANOVA, there were significant differences between the three severity groups of COVID-19 in IL-6, CRP, % neutrophils, lymphocyte count, % lymphocytes, eosinophil count, % eosinophils, NLR, PLR, and urea." (PMID 36838284, 2023). "In COVID-19 patients, CRP has been already described as a bad outcome predictor, together with the cytokines associated with its expression (IL-6, IL-10)." (PMID 37373750, 2023).
COVID-19 (continued). "As reported in our prior study, at 13 months after discharge, 11.6% of the HCWs with severe COVID-19 had elevated IL-6, and more than 98% had normal levels of the remaining five cytokines (IFN-γ, IL-10, IL-2, IL-4 and TNF-α)." (PMID 36908474, 2023). "At the same time, elevated D-dimer values correlate with inflammation markers such as CRP and IL-6, as in severe COVID-19." (PMID 37109161, 2023). "According to IL6 expression, patients with COVID-19 were divided into two groups to analyze hsTnI levels." (PMID 37564653, 2023). "CRP, a biomarker produced by the liver and induced by IL-6, is commonly elevated in severe cases of COVID-19, making it a sensitive marker of inflammation and tissue damage." (PMID 37754237, 2023). "In COVID-19 patients, IL-6 and CRP levels are also disease severity indicators and predict patient survival." (PMID 37568161, 2023). "Secondly, IL-6 was identified as a significant and independent predictor for infiltrate above the median in COVID-19 (p < 0.001), opposite to age, obesity, chronic pulmonary disease, chronic kidney disease, and severe course of disease (each p = n.s)." (PMID 37733154, 2023). "Anti-TNF-α medication has lately been proposed as a strategy for lowering inflammation in COVID-19 patients after IL-6 blocking showed little efficacy." (PMID 37124230, 2023). "Therapeutic modulation of IL-6 levels by anti-IL-6 receptor antagonists (tocilizumab, sarilumab) reduces the duration of COVID-19 and/or reduces the severity of the disease." (PMID 37063919, 2023). "Some of these cytokines, such as IL-1, IL-6 and TNF, have been associated with COVID-19-related mortality and greater severity of the disease." (PMID 37189499, 2023). "Even though the cutoff value for the IL-6 level appears to vary from study to study, these studies have all shown that the monitoring of IL-6 levels helps predict the severity of COVID-19-infected patients." (PMID 36679421, 2023). "Namely, interleukin (IL)-6 is one such cytokine that has received much attention as a biomarker and potential targetable effector of COVID-19 severity." (PMID 37427016, 2023). "Convalescent COVID-19 children had elevated levels of IFNγ, IL-2, TNFα, IL-1α, IL-1β, IFNα, IFNβ, IL-6, IL-12, IL-17A, IL-10 and G-CSF in comparison to control children." (PMID 37013538, 2023). "Monitoring the levels of IL-6 and TNFα has been proposed as a strategy to guide the management of COVID-19 patients as these levels were found to be significant predictors of severity and mortality." (PMID 37055774, 2023). "Pyroptosis was found in COVID-19 patients with increases of IL-1β and IL-18, which further promoted the secretion of pro-inflammatory cytokines such as IL-6, IFN-γ, MCP-1/CCL2, MIP-1α/CCL3, MIP-1β/CCL4." (PMID 37631016, 2023). "Analysis of cytokine at pretreatment showed that the COVID-19 positive patients had significantly elevated levels of IL-17A, IL-6, IL-10, MIG, MCP-1 and IP-10." (PMID 37662953, 2023). "Among infants displaying severe COVID-19 and presenting with pneumonia or gastrointestinal symptoms, high levels of IL-6 were found." (PMID 37047752, 2023). "IL-6 can probably increase and exacerbate the symptoms of COVID-19; therefore, it is possible to utilize anti-IL-6 in the treatment of SARS-CoV-2 infection." (PMID 37158893, 2023). "IL-18 additionally stimulates interleukin-6 (IL-6) and Granulocyte–macrophage colony-stimulating factor (GM-CSF), blockade of which have yielded therapeutics for severe COVID-19." (PMID 36823262, 2023). "The correlation between physical problems (body temperature, blood oxygen saturation level, shortness of breath, coughing, weakness, and lethargy) and interleukin-6 level in COVID-19 patients." (PMID 37692307, 2023). "As a result of the immune host’s antiviral response, neuropsychiatric abnormalities in COVID-19 patients have been correlated with greater levels of pro-inflammatory cytokines, such as IL-6, IL-2, IL-17 and TNF." (PMID 37189896, 2023).
COVID-19 (continued). "Convalescent COVID-19 children had elevated levels of IFNγ, IL-2, TNFα, IL-1α, IL-1β, IFNα, IFNβ, IL-6, IL-12, IL-17A and G-CSF in comparison to control children." (PMID 37013538, 2023). "In contrast, the severe COVID-19 patient group, when compared with mild and healthy control groups, exhibited more significant amounts of IL-6 and IL-1β22." (PMID 37363608, 2023). "In other studies, including the RECOVERY study, patients with COVID-19 treated with IL-6 antagonists (e.g., tocilizumab) had a lower mortality rate at 28 days." (PMID 37298597, 2023). "Tocilizumab was originally proposed as a potential therapy for COVID-19 after markedly elevated serum IL-6 levels were reported in early cases from Wuhan and was associated with reduced survival." (PMID 37629609, 2023). "Among them, however, the main predictors of death by severe COVID-19 patients were IL-6, CRP and platelet count but only during the first wave." (PMID 36817433, 2023). "One of the mechanisms that we identified to be commonly regulated by miRNAs expressed in COVID-19 patients is the interleukin-6/signal transducer and activator of transcription 3 (IL-6/STA3) axis, and this has been proposed previously." (PMID 36834984, 2023). "IL-6 is a powerful pro-inflammatory cytokine that stimulates the C-reactive protein (CRP) and is identified as a driver of the COVID-19 cytokine storm associated with a poor outcome." (PMID 36851766, 2023). "The serum levels of IL-6 were significantly elevated in COVID-19 patients across disease severity (median: 55.2 pg/mL in COVID-19 versus 0.0 pg/mL in healthy patients, Mann–Whitney U P = 0.001)." (PMID 38138084, 2023). "The increase in pro-inflammatory cytokines, including IL-6, IFN-γ, and TNF-α, has been proven in patients with COVID-19 and found to be associated with COVID-19 disease severity, and thus, some patients have responded to IL-6 blockade." (PMID 37602239, 2023). "UCB mesenchymal cells reduce inflammation, including cytokine storms in COVID-19 patients, as indicated by decreased IL-4, IL-6, and IL-10 levels." (PMID 37763198, 2023). "We recently showed that patients with NAFLD have higher levels of IL-6, IL-8, IL-10, and CXCL10, and lower levels of IFN-γ, and these were associated with worse COVID-19 outcomes." (PMID 37375073, 2023). "Recently, multiple studies have shown that the inflammatory markers CRP, PCT, leukocytes, and IL-6 are important predictors of mortality in COVID-19, too." (PMID 37386635, 2023). "In COVID-19, increased levels of IL-6 support the differentiation of pro-inflammatory Th17 cells and a decrease of the T cells, such as CD4+ T cells, CD8+ T cells and natural killer (NK) cells." (PMID 36941580, 2023). "The maximum concentration of IL-6 recorded in the critical form of COVID-19 of a vaccinated patient was 494.8 pg/mL, and the maximum concentration of IL-6 of an unvaccinated patient with the critical form was 5000 pg/mL." (PMID 37239895, 2023). "Hypercoagulability, endothelial dysfunction (increased ICAM-1 levels), and inflammation (increased IL-6 levels) can still be detected in some patients approximately 1 year after recovery from COVID-19." (PMID 37896963, 2023). "The main cytokines produced due to the immune response in severe COVID-19 are interleukin (IL)-1, IL-2, IL-6, and tumor necrosis factor (TNF)." (PMID 37927596, 2023). "A single study reported that in COVID-19 cases, high serum IL-1β and IL-6 in the disease were correlated with critical in-hospital deaths (p = 0.01)." (PMID 37106750, 2023). "Similar results have been observed in recent studies, which indicate the absence of statistically significant differences in the serum concentration of IL-6 between patients of the control group and those recovered from the COVID-19." (PMID 37484856, 2023).
COVID-19 (continued). "As COVID-19 spreads around the world, a series of uncontrolled cases of anti-cytokines (mostly anti-IL-6 and anti-IL-1) are promising and show clear benefits in large-scale controlled trials with corticosteroids." (PMID 37153613, 2023). "An increase in IL-6 levels in the early stage of infection indicates potential deterioration in COVID-19 patients." (PMID 37896795, 2023). "It is evident from Lundström’s and another studies that, in COVID-19, sACE2 concentration rises (3.5 fold) less than that of IL-6 (about 6 fold up to a mean of 32 pg/mL compared to 5 pg/mL in healthy individuals)." (PMID 36851081, 2023). "Here, both COVID-19 vaccines reduced pan-acetylation of the IL6 gene, suggesting that this genic region is less accessible in monocytes from vaccinated individuals." (PMID 37520439, 2023). "The prothrombotic status of COVID-19 can be explained by the increase in coagulation levels of D-dimer, lymphocytes, fibrinogen, interleukin 6 (IL-6), and prothrombin time." (PMID 37240292, 2023). "Serum levels of IL-6, IL-8, and IL-10 were significantly increased in patients with COVID-19, but their predictive value regarding disease severity and the need for oxygen therapy was poor." (PMID 37969879, 2023). "IL-6, IL-6-STAT3, and the NF-κB signaling pathway are markedly activated in hypercytokinemia associated with COVID-19." (PMID 36987476, 2023). "High levels of interleukin-6 (IL-6) and its circulating receptor, which form a complex to induce the inflammatory signal, have been observed in patients with COVID-19." (PMID 36991597, 2023). "We previously conducted a pilot trial administering nasal Foralumab in subjects with mild to moderate COVID-19 and found a reduction in serum IL-6 and C-reactive protein and more rapid clearance of lung infiltrates in treated individuals." (PMID 36881624, 2023). "CRS indicators were critical care services (ICU) admission, mechanical ventilation, increased intubation rates, elevated interleukin-6, clinical severity of COVID-19, and inpatient services." (PMID 36909058, 2023). "For example, IL-6 plays a pivotal role in the pathophysiology of cytokine-driven hyperinflammatory COVID-19 status, and its serum levels have been strongly correlated with elevated transaminases levels in hospitalized patients with COVID-19." (PMID 36674607, 2023). "The COVID-19 patients with myocardial injury had elevated IL6 expression and decreased lymphocyte counts." (PMID 37564653, 2023). "Regarding the percentage of pulmonary infiltrates in COVID-19, stepwise multiple linear regression analyses adjusted for the potential confounding variables were performed separately for each IL-6, CRP, and leucocytes." (PMID 37733154, 2023). "This is in contrast to other reported data whereby the level of IL-6 was found to be higher in COVID-19 patients compared to healthy controls and was highly associated with disease severity and disease progression." (PMID 37228441, 2023). "In fact, circulating levels of IL-6 are significantly lower in patients with COVID-19 than in patients with sepsis." (PMID 37051234, 2023). "COVID-19 induces an increase in cytokine levels, including tumor necrosis factor, interleukin-1, interleukin-6, procalcitonin, and interferon." (PMID 36798637, 2023). "Tocilizumab (TCZ) and sarilumab, both of which are monoclonal antibodies that block IL-6, showed benefits in COVID-19 when given early." (PMID 36987476, 2023). "The levels of the pro-inflammatory cytokine IL-6 were generally increased at diagnosis in the COVID-19 male patients, while they were decreased in the same patients at follow-up but were still elevated after 5 months compared to healthy controls (p = 0.049)." (PMID 37896963, 2023). "C-reactive protein (CRP), Tumor Necrosis Factor-α (TNF- α), interleukin-6 (IL-6), IL-8, CXCL10, peripheral inflammation biomarkers linked to COVID-19 severity, also predict sequelae, as well as Type I and Type III interferons (IFN)." (PMID 38235145, 2023).